CD4 (CD4 molecule)
Diseases named in the same sentence as CD4 in open-access papers (continued):
Sharing a sentence is not in itself a finding about the gene and the disease.
tumor (continued). "Specifically, five studies have reported a significant increase of CD4+ T-cell infiltration in the peritumoral region, compared to the tumor center in ICCA." (PMID 38213535, 2023). "Various subtypes of CD4+ T cells have different and even opposite functions like antitumor activities or tumor-promoting processes." (PMID 36949948, 2023). "Although CD8 T cells have been proven to be major contributors of tumor clearance following ICB treatment, GZMA and PRF1 expression in MSI-H tumors was also associated with high levels of activated memory CD4+ T cells, γδ T cells and macrophages." (PMID 37492581, 2023). "We observed few scanty CD4+ T cells in all four GBMs, with the highest density observed in the tumor of II:4 (159.63 ± 107.13/mm2)." (PMID 37529690, 2023). "Although, not significant, negative correlations between CD73 gene expression and CD8+ T cells, CD4+ activated T cells and activated NK cells were observed in the tumor samples." (PMID 37392167, 2023). "CD4 T cells have crucial effect on almost every aspect of immunity and are considered an important component needed in tumor immunotherapy." (PMID 37082103, 2023). "Mechanistically, we show that the increase in PD-L1 expression in tumor cells is directly induced by CD4+ T cells." (PMID 36239683, 2023). "CD4+ T cells play a central role in regulating anti-tumor immune responses by secreting cytokines to activate other immune cells such as CD8+ T cells and macrophages." (PMID 37744350, 2023). "Compared to the C2 subtype, the C1 subtype showed better prognosis with increased CD4 positive memory T cells as well as activated dendritic cells (DCs) infiltration and suppressed M2-phenotype macrophages inside the tumor microenvironment." (PMID 37908977, 2023). "Tumor growth was rescued upon depletion of CD8+ T cells, supporting a model whereby the reduction in tumor growth in Cd4; Tcf7fl/fl mice was CD8+ T cell dependent." (PMID 36239683, 2023). "Of note, 40% of TRP-1 CD4+ T cells isolated from CD4 ACT-treated mice produced IFNγ following stimulation with tumour lysate-pulsed dendritic cells, confirming their TH1 phenotype." (PMID 37316667, 2023). "The clinical prognosis of CD4+ T cells from the blood of patients with cancer, together with the assessment of tumor cell-directed CD4+ T cells, can reveal the relevance of CD4+ T cell responses in cancer immunotherapy." (PMID 38328405, 2023). "Although MDR1 remains widely viewed as a simple drug efflux pump in tumor cells, recent evidence suggests that this transporter fills key endogenous roles in enforcing metabolic fitness of activated CD4 and CD8 T cells." (PMID 38022644, 2023). "Here, we demonstrated that increasing RECK expression is distinctly associated with the ESTIMATES score, especially CD4+ and CD8+ T infiltrating cells in the tumor microenvironment of GC." (PMID 37904179, 2023). "The majority of the CD4 T cells in the HT-29 tumor cell killing assay were PD1+IL7R-CD107a+, resembling the phenotype of the intratumoral C1-PRF1 CD4 T-cell population identified by scRNAseq." (PMID 37185301, 2023). "Activated CD4+ or CD8+ T cells can also produce anti-tumor cytokines such as IFN-γ to inhibit tumor growth and recruit other immune cells." (PMID 36639648, 2023). "HT-29 tumor cell killing by tumor CD4 T cells was accompanied by markedly increased intracellular expression of perforin and GZMB, as well as the surface expression of CD107a, a marker for degranulating CTLs." (PMID 37185301, 2023). "Further research is necessary to design an effective vaccine that will induce a tumor-specific CD4+ T cell response." (PMID 38005965, 2023). "Survival analyses of raw CD4+, CD8+, and CD45+ tumor-infiltrating immune cell percentages revealed that the higher the CD4+ (p = 0.0028) and the CD45+ (p = 0.0221) infiltration within the FFPE samples was, the longer the overall survival (OS) of the patients." (PMID 37761986, 2023).
tumor (continued). "Immunohistochemical staining of CD4 and CD8 in tumor samples from days 14 and day 21 showed increased CD4+ and CD8+ T cells in the r4T1-MBTA group." (PMID 37434263, 2023). "CD4+ T cells isolated from tumor tissue downregulate granzymes B and H and upregulate genes associated with regulatory T cells (FOXP3, IKZF4, CD38, ISG15)." (PMID 37648263, 2023). "A good response to NET defined as a decrease in tumour size and/or decrease of Ki‐67 was found to be associated with a longer duration of NET, a change of CD4+ T‐cells, and a higher number of CD68+ tumour‐associated macrophages before the start of NET." (PMID 37553911, 2023). "In our model, CD8+ T cells play a direct role of tumor killing, whereas CD4+ T cells kill cancer cells through cytokines they produced." (PMID 36766849, 2023). "One of these CNs was enriched for MHCI+ tumor cells, CD4+ T cells, Ki67+ CD4+ T cells, and NK cells (termed herein Productive T cell & Tumor CN)." (PMID 38085642, 2023). "In the meanwhile, the last 5 years have seen many reports recognizing the critical role of CD4+ T cells driving anti-tumor immunity and in supporting anti-tumor CD8+ T cell responses." (PMID 37287989, 2023). "Fascinatingly, during the early stages of this anti‐tumor immune response, CD4+ T cells play a crucial role in specifically recognizing the tumor." (PMID 38062888, 2023). "Tumor‐infiltrating CD4+ and CD8+ lymphocytes exhibited a higher proportion of cells positive for CD107a, CD25, markers of lymphocyte activation." (PMID 37587833, 2023). "It has been demonstrated that while higher levels of CD8+, CD4+, and CD3+ T cells in tumor stroma are associated with better overall survival (OS), FOXP3+ T cell infiltration leads to decreased OS in NSCLC patients." (PMID 37509394, 2023). "PD-L1 is mainly released by tumor cells and mature dendritic cells and can induce apoptosis of CD4+ and CD8+ T lymphocytes." (PMID 37314514, 2023). "Tregs, a specific type of CD4+ T cells, are attracted to the tumor area by chemical signals released by tumor cells and macrophages, and they help prevent autoimmune diseases." (PMID 38067304, 2023). "Activated natural killer cells (NKs) and cytotoxic T lymphocytes (CTLs, which are CD8+ T cells) possess the ability to kill tumor cells with the help of CD4+ T cells 46-49." (PMID 36632233, 2023). "The percentage of Tregs, T cells follicular helper, T cells CD8, T cells CD4 memory active, NK cells activated, Macrophages M1, and naive B cells were relevant to the NI of most tumor types." (PMID 37351504, 2023). "At the time of tumor response initiation (i.e., post 3 IV injection), a higher level of tumor infiltration by CD4 T-cells was observed in the high-dose Lipo-MP-LPS group, but not in the low-dose group, compared to control group (p < 0.005)." (PMID 37760603, 2023). "Apoptosis assay showed that the proportion of apoptotic cells increased remarkably in tumor cells (H22 cells and S180 cells) treated with Th1 cells compared with naïve CD4+ T cells (p < 0.05)." (PMID 36690649, 2023). "Previous studies have also shown the anti-tumour immunity, induced by vaccines, through CD4+ T cell response in melanoma." (PMID 37037839, 2023). "Upon T-cell receptor activation, naïve CD4 T cells can differentiate into distinct Th lineages with protumoral or antitumoral activity and actively shape tumor immunity." (PMID 37448553, 2023). "In the HC_HE compartment, an average of 88.5% of cells in CD8 + clusters belonged to overrepresented clusters within a given tumor (#3, #4, #9, #11, #21), while an average of 81.4% of CD4 + T-cells belonged to CD4 + FOXP3 + (cluster #2)." (PMID 38057799, 2023). "Proteasome processing of tumor antigens and presentation in MHC II are critical for tumor recognition by CD4+ T cells." (PMID 37287989, 2023).
tumor (continued). "In TILs, we observed an enrichment in gene signatures associated with cytotoxicity, T cell exhaustion, NOTCH signaling, and CD4 TReg cells, indicating their functional characteristics within the tumor microenvironment." (PMID 38067255, 2023). "Regulatory T cells (Treg) are a subclass of CD4+ cells that specifically express Forkhead box protein 3 (Foxp3) and are critical in regulating the anti-tumor response of T cells in the tumor microenvironment." (PMID 36831655, 2023). "LAG3 expression was detected immunohistochemically in the membrane of tumor-infiltrating lymphocytes and on tumor-infiltrating CD4 or CD8 cells in MPM." (PMID 38062416, 2023). "Our immunoanalysis also suggested that the tumor infiltration by CD4 and CD8 T-cells induced by Lipo-MP-LPS is associated with the activation of CD4 and CD8 T-cell responses in periphery." (PMID 37760603, 2023). "In summary, our research provides initial insights into how TAGAP affects CD4+ T cell differentiation and function within the tumor microenvironment through the STAT pathway, thereby inhibiting LUAD malignancy progression." (PMID 37744350, 2023). "This complex role has led to an ongoing debate regarding the impact of CD4 T cells on tumor prognosis." (PMID 38132439, 2023). "Prior to treatment with anti-PD-1 in this model, the tumor microenvironment was observed to support an immunosuppressive environment to promote tumor growth, with greater proportions of CD-4+ to CD-8+ T cells." (PMID 37259381, 2023). "The trial followed preclinical results in which cabozantinib with anti-PD1 showed to slow tumor’s growth and increase expression of the CD4+ T cell ligand HLA-DR on the tumor cells themselves." (PMID 37207140, 2023). "While CD8+ T cell depletion significantly restored tumor growth in mice receiving dual IL-6/CTLA-4 blockade, CD4+ depletion resulted in pronounced tumor growth." (PMID 36881480, 2023). "In this trial, ATLAS was used to identify neoantigens in each patient’s tumor, recognized by their CD4 and/or CD8 T cells, and the identified neoantigens were incorporated into a patient’s personalized vaccine in the form of SLPs." (PMID 36992219, 2023). "For example, naïve CD4 + T cells (c1) were abundant in blood but rare in tumours, whereas exhausted CD8+ T cells (c11) were abundant in tumours but rare in the blood." (PMID 37596248, 2023). "Among the T-cell subpopulations, the percentage of both tumor-infiltrated CD4+ T cells and CD8+ T cells was increased by 10- and 6-fold, respectively, in the tumors of the B16F10-IL9+BMDM group." (PMID 36968220, 2023). "Instead, patient #5 presented a mTDLN with a low HLA-I tumor expression but a high percentage of CD4+ T cells (44%) and a high number of CD20+ nests in the peritumoral area before treatment with interferon alpha-2b." (PMID 37691949, 2023). "In cancer, neoantigen (NeoAg)-specific CD8+ T cells capable of direct tumor recognition have been extensively studied but little is known of the role of NeoAg-specific CD4+ T cells." (PMID 37400675, 2023). "In the last few decades, the function of tumor-infiltrating lymphocytes (TILs), especially the cytotoxic CD8+ T cells and other subgroups of T cells, such as CD4+ T cells and Tregs on tumor progression and patient prognosis have been deeply explored." (PMID 36960057, 2023). "Data were then split into CD4+ and CD8+ T cell subsets and compared by expressed TCR allele count in blood or combined tumor and normal tumor-adjacent tissues." (PMID 37129560, 2023). "These cells were first recognized by IP challenge in the donor mice demonstrating that a high clonotype response to challenge is a reliable method to identify anti-tumor CD4 and CD8 T-cell clones." (PMID 37033929, 2023). "Tumor-infiltrating Tregs can comprise up to 50% of intratumoral CD4+ T cells, exhibiting a more proliferative and immunosuppressive phenotype." (PMID 37868998, 2023).
tumor (continued). "PDOX treatment also induced the highest level of circulating CD431B11+ CD4+ T cells on day 13 and day 18 post tumor challenge compared with other treatment groups (anti-OX40/CpG and anti-PD-L1) and untreated mice." (PMID 36796366, 2023). "Ldha/b-DKO mice exhibited decreased numbers of tumor-infiltrating CD4+ and CD8+ T cells and decreased frequencies of tumor-infiltrating IFN-γ–producing and granzyme B–producing CD4+ and CD8+ effector T cells." (PMID 36821379, 2023). "Taken together, our data suggest that CD4 CTLs can mount specific, HLA-II-restricted killing of HT-29 tumor cells via the perforin and TNFα pathways." (PMID 37185301, 2023). "Based on automated image analysis using an automated epifluorescence microscope, we found a statistically significant increase in the number of CD8 + T and NK cells, except for CD4 + T cells in post nCRT tumor samples." (PMID 35794399, 2023). "For peptide cancer vaccines to be effective, they must contain both CD8+ and CD4+ epitopes to activate cytotoxic T lymphocytes (CTL) anti-tumor immunity and T helper cell activation to sustain the CTLs effector function." (PMID 36999039, 2023). "We therefore evaluated, during the early phase of tumor formation and after two days of treatment (T2), the number of PD-1+CD4+ and PD-1+CD8+ in TDLNs of NB-bearing mice." (PMID 36854895, 2023). "But further intense investigations are needed to understand the molecular characteristics and development of tumor-specific CD4+ CTL in solid cancers in order to boost their anti-tumor activity." (PMID 37965314, 2023). "Regulatory CD4+ T-cells in the BC TIME have been associated with adverse outcomes, similar to other tumor types." (PMID 37727793, 2023). "Within the tumor infiltrating CD4+ population CD39 expression is found on both conventional T cells and Foxp3+ Tregs." (PMID 37648263, 2023). "We observed consistency in immune population distribution and activation status between 4T1.2 and 4T1.2-HER2T tumours and TdLN, except for increased CD4+ T-cells within the subcutaneous 4T1.2-HER2T TdLN." (PMID 37153626, 2023). "Conversely, IDO1 knockdown restored the percentage of Granzyme B+ CD8+ T cells and reduced the frequency of CD25+FOXP3+ CD4+ T cells within tumor tissues derived from USP14-overexpressing cancer cells." (PMID 37830596, 2023). "Low lymphocyte counts indicate an insufficient host immune response and are associated with adverse clinical outcomes, perhaps due to a reduced level of CD4+ T cells, which impairs tumor suppression and defense." (PMID 36980755, 2023). "After tumor resection, the proportion and absolute number of CD4+Tcm significantly decreased, while those of CD4+Tem significantly increased, compared with preoperative values." (PMID 36925914, 2023). "Memory CD4 cells, macrophages M0, and plasma cells are the most common tumor-infiltrating immune cells." (PMID 37524774, 2023). "Further research is needed to investigate how MTLM genes regulate tumor progression through CD4 T cells." (PMID 37994323, 2023). "Cyclophosphamide pretreatment and innate immune stimulation were required in our CD4 ACT protocol to eradicate established tumours, similar to our findings for CD8 ACT24." (PMID 37316667, 2023). "Using intravital imaging of the bone marrow to quantify killing events in the sensitive tumor model, we established that perforin-dependent killing account for less than a third of tumor cell death during CD4+ CAR T-cell therapy." (PMID 37248395, 2023). "On the contrary, high levels of CD4+Foxp3+ or Treg cells through IL-4 and IL-10 production have been correlated with immunosuppression and pro-tumor activity, triggering poor outcomes." (PMID 37370836, 2023). "When we used anti-CD25 to deplete CD25-expressing Treg cells, we observed that the enhanced tumor burden in Chatfl/fl; Cd4-cre mice was partially decreased." (PMID 37640929, 2023).
tumor (continued). "We also observed depletion of sgRNAs targeting genes with known function in tumor immunity and/or resistance to immune-checkpoint therapy, such as CD4, C1qb in KrasG12D lungs." (PMID 37258521, 2023). "Next, we examined the number of tumor-infiltrating T cells by immunohistochemical staining of CD4 or CD8." (PMID 37046033, 2023). "Similar to our findings, a related study reported that exacerbated infiltration of CD4 memory T cells occurred at the tumor sites." (PMID 37346073, 2023). "The comparison of co-expression of checkpoint molecules between the different ROIs illustrated higher levels of CD4 with CTLA-4 in the sclerotic tumor compared to the interface (p = 0.02)." (PMID 36980192, 2023). "Specifically, samples of laryngeal origin showed the lowest cytotoxicity (lowest CD8+/CD4+ T-cell and NK-cell infiltration) and high prevalence of tumor-promoting M2 macrophages and neutrophils, while the oropharynx samples exhibited opposite trends." (PMID 37819239, 2023). "We then evaluated the ability of NVs to capture antigens in vitro, which would allow NPs to further deliver tumor antigens to APCs for antigen presentation and antitumor CD4+ and/or CD8+ T cell responses." (PMID 37450588, 2023). "Future studies will need to confirm the extent to which B cells present TERT and activate CD4 helper T cells, reshaping the immune response in the tumor microenvironment." (PMID 36909826, 2023). "In tumor immunotherapy, the synergistic effect of CD4+ T and NK cells is stronger than that of CD8+ T cells." (PMID 37346073, 2023). "T‐lymphocyte expression is linked to poor prognosis and tumor metastasis, such as CD3+,61 CD4+,62 CD4+/CD8+ T cell ratio, and NK cells, increasing immune function to inhibit tumor growth." (PMID 35650714, 2023). "We have shown the participation of Tag7 exposed on the cell membrane of cytotoxic CD4+-T lymphocytes in the cytolysis of Hsp70-positive tumor cells by these lymphocytes." (PMID 37511122, 2023). "The vaccine induced potent tumor-specific CD4+ and CD8+ T-cell responses in mice and protected 60-80% from lethal tumor challenge." (PMID 37063845, 2023). "Analysis of CD8+ T cells and CD4+ cells in tumor after treatment showed that the proportion of CD8+ T cells decreased both in 9 and 15 DPT." (PMID 36969873, 2023). "Findings included increased CD8+ T cell infiltration, Th1 polarisation of CD4+ T cels and M1 macrophage differentiation, with upregulation of PD-1 expression in intra-tumoural effector T cells." (PMID 37686543, 2023). "Important grade-associated adaptive immune cell features indicated reduced adaptive immune cell involvement with less differentiation in the tumor: CD4+ memory T cells were smaller and less dense in higher grade tumors." (PMID 38125025, 2023). "As immature dendritic cells start to mature, antigen-loaded dendritic cells migrate to the cervical lymph nodes, where they present tumor antigens to CD4+ and CD8+ T cells." (PMID 37509316, 2023). "CD4+ T cells are mainly involved in immune responses within the tumor microenvironment and over time differentiate into several cells." (PMID 36672326, 2023). "When we compared final tumor weight and tumor-to–body weight ratio, we noticed a significant reduction in tumor growth in Cd4;Tcf7fl/fl mice compared with control hosts." (PMID 36239683, 2023). "Subsequently, to assess the effect of TAGAP on CD4+ T cell cytotoxicity, we co-cultured tumor cells with activated CD4+ T cells at different target-to-effector cell (T:E) ratios of 1:2, 1:3, and 1:5." (PMID 37744350, 2023). "Overall, it is clear that stimulation elicits a high-frequency oligoclonal anti-tumor response of at least 1 CD4 and 3 CD8 memory T-cell clones." (PMID 37033929, 2023). "Results from ssGSEA showed patients in the low-risk group had significantly more B cells, CD4/CD8+ T cell and MDSC infiltrating the tumor." (PMID 37197421, 2023).